CHPF2 (chondroitin polymerizing factor 2)
Description:
Non-catalytic component of CHSY1-CHPF2 and CHSY3-CHPF2 chondroitin sulfate synthase complexes. CHPF2 associates with catalytically active chondroitin synthases (CHSY1/3) within heterodimeric complexes. Plays an essential role for the formation of a stable and functional chondroitin sulfate polymerase complexes.
Synonyms: ChPF-2; ChSy-3; CSGLCAT; KIAA1402; CSGlcA-T
Tractability: Antibody: UniProt predicts a signal peptide or a membrane-spanning region. PROTAC: ubiquitination databases record sites on it; its protein half-life has been measured.
Gene: Protein-coding gene on chromosome 7 (151,232,483 to 151,240,979, forward strand). Ensembl gene ENSG00000033100.
Subcellular location: Golgi apparatus membrane
Subcellular location (Human Protein Atlas): Cytosol; Nucleoplasm
Pathways (Reactome):
Metabolism: CS-GAG biosynthesis
Gene Ontology:
Molecular function: acetylgalactosaminyltransferase activity; N-acetylgalactosaminyl-proteoglycan 3-beta-glucuronosyltransferase activity; protein-macromolecule adaptor activity; glucuronosyl-N-acetylgalactosaminyl-proteoglycan 4-beta-N-acetylgalactosaminyltransferase activity
Biological process: chondroitin sulfate proteoglycan biosynthetic process
Cellular component: Golgi apparatus; membrane; Golgi membrane; Golgi cisterna membrane
Genetic constraint (gnomAD): Loss-of-function variants: 58 observed, 63.53 expected, observed/expected ratio (o/e) 0.91, 90% interval 0.74 to 1.14. The upper end of that interval is the gene's LOEUF score, 1.14, which puts it in group 4 of 6, group 1 being the genes least tolerant of losing a copy. Missense variants: 1,045 observed, 1,050.8 expected, observed/expected ratio (o/e) 0.99, 90% interval 0.94 to 1.05. Synonymous variants: 442 observed, 445.15 expected, observed/expected ratio (o/e) 0.99, 90% interval 0.92 to 1.07.
Homologues: Orthologues: chimpanzee CHPF2 (99% identical), macaque CHPF2 (99% identical), pig CHPF2 (98% identical), rabbit CHPF2 (98% identical), dog CHPF2 (97% identical), guinea pig CHPF2 (96% identical), mouse Chpf2 (95% identical), rat Chpf2 (95% identical), zebrafish chpf2 (60% identical), tropical clawed frog chpf2 (53% identical), Drosophila melanogaster Chpf (29% identical), Caenorhabditis elegans mig-22 (26% identical). Paralogues in human: CHPF (57% identical), CHSY3 (22% identical), CHSY1 (21% identical), B4GALNT4 (17% identical), B4GALNT3 (16% identical), CSGALNACT2 (13% identical), CSGALNACT1 (12% identical).
Diseases named in the same sentence as CHPF2 in open-access papers:
CHPF2 is named in the same sentence as 11 diseases in open-access papers, as found by Europe PMC text mining. Sharing a sentence is not in itself a finding about the gene and the disease. The quoted sentences say what the papers report.
breast carcinoma (2 papers, 2021 to 2023). "CHPF2 acts as an oncogene that is up-regulated in cancers to exert its positive role in cell proliferation and metastasis, including breast cancer, hepatocellular carcinoma, lung adenocarcinoma, etc.." (PMID 34195087, 2021). "A search for reports (PubMed) of known activities of these genes in breast cancer showed that only three (CHPF2, KEL, and CCT6P1) have not yet been associated with this cancer." (PMID 36900209, 2023).
colon cancer (1 paper, 2021). "qRT-PCR was performed from RNA extracted from 43 pairs of colon cancer and adjacent normal tissues to observe the relative expression levels of eight GRGs (P4HA1, STC2, CHPF2, PMM2, PGM2, ENO3, PPARGC1A, and PPP2CB)." (PMID 34422808, 2021).
CHPF2 also shares sentences with these, for which no sentence is quoted: cancer (3 papers); Coffin-Siris syndrome (1); colon adenocarcinoma (1); hepatocellular carcinoma (1); lung adenocarcinoma (1); melanoma (1); mental retardation (1); rectum adenocarcinoma (1); thyroid cancer (1).